INS (insulin)
Diseases named in the same sentence as INS in open-access papers (continued):
Sharing a sentence is not in itself a finding about the gene and the disease.
diabetes (continued). "This study looks at the predictive value of substitution of HH ratio with the “Diabetes mellitus on insulin” component of RCRI in diabetic patients going for non-cardiac operations." (PMID 37035307, 2023). "As a result, mice lacking either ICA69 or PICK1 developed diabetes-like phenotypes, such as glucose intolerance, due to defective insulin secretion when they turned half to 1 year old." (PMID 37251649, 2023). "Fasting insulin secretion rates and insulin secretion rates during the hyperglycemic clamp were unchanged by exendin 9-39 infusion in people without diabetes." (PMID 37751301, 2023). "Fifth, our study of diabetes medications did not include insulin because the days’ supply of insulin is difficult to interpret owing to variable (ie, sliding-scale) dosing." (PMID 37195661, 2023). "Ninety-five patients (81%) had no comorbidities other than diabetes and 111 patients (94%) had no treatment other than insulin." (PMID 38188912, 2023). "When we stratified models on medication use, disparities were evident across all strata, but were especially large among adults not using diabetes medication and among individuals using both insulin and oral hypoglycemic agents." (PMID 37796503, 2023). "Obesity and diabetes are significantly associated with the development of nonalcoholic fatty liver disease (NAFLD), especially when the patients are treated with insulin." (PMID 36942499, 2023). "However, Wnt4 expression in islet cells of individuals with diabetes is increased, leading to enhancement of the JNK pathway in Wnt/PCP signaling, which impairs β cell proliferation and insulin secretion." (PMID 37106471, 2023). "Vaccarin, an active flavonoid glycoside extracted from vaccariae semen, reduced blood glucose, increased glucose and insulin tolerance, and relieved glucose metabolism disturbances in STZ/HFD-induced type 2 diabetes mellitus (T2DM) mice by regulating miR-34a expression." (PMID 37687031, 2023). "For example, "lean (pre)diabetes" patients tend to have a rapid beta-cell failure rather than insulin resistance." (PMID 36804876, 2023). "68.6% were pregnant with their first child; 93.9% did not use insulin for blood glucose control, and 75.1% had no family history of diabetes." (PMID 38026370, 2023). "No final cure for diabetes has been established yet; however, insulin and other BG-lowering agents are used to stabilize blood levels and avoid diabetic complications." (PMID 38111457, 2023). "Diabetes mellitus is majorly classified into type-1 DM (i.e., insulin-dependent) and type-2 DM (non-insulin-dependent) with the latter accounting for 90–95% of DM incidence." (PMID 37969920, 2023). "Many people with T2D do not want insulin because they worry about weight gain, hypoglycaemia, and painful injections and perceive their diabetes has progressed." (PMID 37237318, 2023). "Diabetes runs in the family both in the first and second-generation members, and no one is using insulin." (PMID 37511676, 2023). "T1DM mice are leptin deficient due to decreased fat mass resulting from uncontrolled diabetes unlike humans with T1DM that receive insulin therapy." (PMID 36674935, 2023). "Increased glucagon signaling leads to dysregulated glucose homeostasis, whereas a decrease in glucagon action improves glycemic index in diabetes independent of insulin sensitivity." (PMID 36866247, 2023). "Only 11 (48%) subjects in the well-controlled diabetes group and 10 (37%) subjects in the poorly controlled group were not receiving insulin treatment (p = 0.74)." (PMID 37998569, 2023). "Results showed that hesperidin improved fasting serum glucose without altering insulin levels, indicating improved insulin sensitivity and prevention of insulin resistance and diabetes." (PMID 38234970, 2023). "Recent reviews have identified the role of defective insulin secretion in the pathophysiology as opposed to peripheral insulin resistance observed in classical diabetes." (PMID 37601212, 2023).
diabetes (continued). "In addition, the treatment with the two drugs decreased the incidence of type 1 diabetes mellitus, T2DM, insulin resistance, glucagon signaling pathway, and nonalcoholic fatty liver disease (NAFLD)." (PMID 36778868, 2023). "Data from several studies have identified young patients with diabetes as more prone to medication non-adherence, especially insulin." (PMID 36745515, 2023). "Overall, the PK activator enhanced the ability of insulin secretion but also consolidated glycolysis without increasing glucose oxidation, suggesting a potential therapeutic approach for diabetes based on PK activation." (PMID 37108143, 2023). "Type 1 diabetes mellitus (T1DM) and T2DM have different pathogenesis: T1DM is due to the gradual loss of insulin-producing cells, resulting in low or no insulin production; insulin resistance." (PMID 36818396, 2023). "Skills for supporting people with starting insulin used to be the preserve of hospital diabetes clinics, but the growing population of T2D means this no longer provides value." (PMID 37237318, 2023). "Ketoacidosis is induced either by uncontrolled type 1 diabetes mellitus with a complete lack of insulin signaling or extreme alcohol consumption paired with severe caloric restriction." (PMID 40757529, 2023). "Type 2 diabetes (T2DM) defined as the adult-onset type that is primarily not insulin-dependent, comprises over 95% of all diabetes mellitus (DM) cases." (PMID 36845280, 2023). "Thus, an imbalanced thrombin generation might be a predominant contributor to the excess thromboembolic risk in patients with insulin-requiring diabetes, whereas a balanced thrombin generation could explain the comparable thromboembolic risk in those with diabetes not on insulin and no diabetes." (PMID 35976428, 2023). "When a pregnant woman who does not already have diabetes is unable to produce enough insulin, GDM develops." (PMID 38046782, 2023). "On the other hand, the patient no history of medication of potassium excretion diuretics and large doses of insulin, no hyperthyroidism, no diabetes ketoacidosis, no medication of β2 receptor agonists, which can lead to potassium ion intracellular migration." (PMID 37058043, 2023). "On the contrary, both the prevalence of diabetes and HbA1c values were higher among men with AAA at ultrasound screening in unadjusted analysis, and furthermore adjusted analysis of s-insulin levels after OGTT confirmed relative hyperinsulinemia in men with AAA." (PMID 37731907, 2023). "(iii) Certain indications related to diabetes and IR were absent from the raw data, including waist-to-hip ratio, waist circumference, and insulin concentration." (PMID 36817911, 2023). "Second, although the severity of diabetes mellitus was adjusted through prescription of oral hypoglycemic agents or insulin and fasting blood glucose, HbA1c level was not applied for multivariate adjustment." (PMID 36803488, 2023). "Through genome-wide association meta-analyses of more than 100000 individuals of European ancestry without diabetes, FTO rs1421085 SNP was found to be significantly associated with fasting insulin levels." (PMID 37416800, 2023). "This was initially described as a diabetes phenotype common in the young (age <30 years), with clinical features of malnutrition, not prone to ketosis, receiving high insulin doses, and living in deprived socioeconomic settings." (PMID 36778553, 2023). "In our study, there were only 16 patients received insulin in combination, and more than half of them did not specify the type of diabetes." (PMID 37383395, 2023). "In our case series, in multivariate analysis, duration of diabetes, diabetic foot, diabetic neuropathy, agriculture occupation, those under OHA or insulin or both as compared to those under diet only, PVA > 0.3LogMAR, were significantly associated with any type of DR and VTDR." (PMID 37872518, 2023).
diabetes (continued). "Most importantly, this kind of model does not noticeably decrease body weight or insulin levels but rather develops moderate hyperglycemia and mild diabetes." (PMID 37859703, 2023). "The impairment of the mitochondria’s function as a glucose sensor, which links glucose metabolism to insulin release, contributes to the mechanism of diabetes in PMDs in addition to decreased insulin secretion brought on by a lack of ATP supply." (PMID 38069070, 2023). "Bone resorption marker RatLaps (CTX‐I) was not altered because of diabetes, insulin, or antibody treatment." (PMID 38025035, 2023). "Acute hyperglycemia is common in hospitalized patients, both those with and those without recognized diabetes, and basal plus bolus insulin therapy is emerging as the optimal treatment strategy." (PMID 36767972, 2023). "Notably, we also found that the “Maturity Onset Diabetes of the Young (MODY)” gene category, which contains genes important for pancreatic β‐cells, including insulin, was among the downregulated enriched gene categories in TFEB‐overexpressing cells." (PMID 37712288, 2023). "NOD mice harbouring Ins1-Cre or a reduced dose of insulin genes show a lower diabetes penetrance but no major changes in autoantibodies or insulitis, and swapping the mouse Ins1 gene for the human INS gene also has a protective effect in NOD mice." (PMID 37488322, 2023). "In the “Maturity onset diabetes of the young” pathway, the upregulation of HHEX and downregulation of HES1 could increase the expression of NEUROG3 and outcomes such as the Insulin signaling pathway." (PMID 36835058, 2023). "In the biomarker cohort (n = 100), there were 27 patients with diabetes (27%), of whom 19 (70.4%) were on oral medication only, 4 (14.8%) on insulin, and 4 (14.8%) on no medication." (PMID 36765354, 2023). "Diabetes is a glucose homeostasis disorder occurring when the pancreas does not make enough insulin leading to high blood glucose levels, or when the body is unable to use it properly." (PMID 36832834, 2023). "It is worth pointing out that the duration of diabetes history, the difference in the frequency of HbA1c measurement and the proportion of insulin therapy was not statistically significant." (PMID 37775768, 2023). "However, the insulin secretion in people with diabetes is impaired, and therefore, increased insulin resistance associated with high triglycerides could not be sufficiently compensated by an increase in insulin secretion." (PMID 35905014, 2023). "Among those with diabetes, 69% took oral antidiabetic medication, 4% used insulin alone, 17% used insulin plus oral drugs, and 10% used neither insulin nor oral antidiabetic drugs." (PMID 37634017, 2023). "Diabetes is a disorder resulting from a lack of insulin production or inadequate utilization of insulin by the organism." (PMID 37954696, 2023). "Other baseline patient characteristics such as BMI, diabetes duration, and total daily dose of insulin, do not appear to clearly predict response." (PMID 37589043, 2023). "The relationship between low carbohydrate diets and glucose and insulin control has been studied in both non-non-diabetes and diabetes patients." (PMID 37299581, 2023). "The most widespread kind of diabetes is type 2, which affects adults and occurs when the body becomes resistant to insulin or does not generate enough." (PMID 36903746, 2023). "According to the Wisconsin Epidemiology Study for Diabetic Retinopathy (WESDR), the prevalence of PDR is 23% in patients with an earlier onset of diabetes, 10% in those with a later onset of diabetes, and 3% in those who do not take insulin." (PMID 38201340, 2023).
diabetes (continued). "Injectable insulin treatment is the most used to treat type 1 diabetes mellitus (DM1) and, in many cases, type 2 diabetes mellitus (DM2); however, factors such as pain of application and inconvenience associated with injections are among those contributing to low adherence to this treatment." (PMID 36982517, 2023). "Half (4/8, 50%) of the participants were taking oral medication, insulin, or traditional medicine for diabetes, whereas the other half (4/8, 50%) were not following any treatment plan for diabetes." (PMID 37721799, 2023). "This knowledge should further encourage investigations into the beneficial effects of promising therapeutic approaches which could improve central insulin sensitivity and GLUT4 expression, to fight diabetes-related cognitive dysfunctions." (PMID 38003671, 2023). "The diabetes insulin self-management education (DIME) intervention study aims to reduce the negative psychological impact of insulin treatment and improve confidence in insulin self-management." (PMID 37237318, 2023). "Current drugs, such as insulin, metformin, sulfonylureas, and acarbose, can control hyperglycemia, but their effect on preventing the complications of diabetes is not ideal." (PMID 36615556, 2023). "In people without diabetes, the incremental increase in integrated insulin concentrations during the first 30 minutes of hyperglycemia was decreased by exendin 9-39 infusion (3.0 ± 0.5 nmol/L versus 1.8 ± 0.3 nmol/L per 30 minutes, P < 0.01)." (PMID 37751301, 2023). "Given the differences in systemic diabetes medications within each diabetic cohort, metabolite comparisons were also made with and without metformin, insulin, and glimepiride." (PMID 36652491, 2023). "16% of the participants managed their diabetes through dietary measures alone, 58% used oral hypoglycaemic agents, but not insulin, and 25% were insulin-treated." (PMID 37745288, 2023). "Finally, the ability of these PVs for transdermal insulin delivery by using PVA/PVP microneedle patches was carried out and the appealability of this platform, probably for the treatment of diabetes in vivo, was suggested." (PMID 36982244, 2023). "Type 1 diabetes mellitus (T1DM) is characterized by a lack of insulin since the beta cells that produce insulin in the pancreas have been destroyed." (PMID 38022113, 2023). "In patients with type 2 diabetes mellitus (T2DM), those receiving oral glucose-lowering medication and long-acting insulin displayed higher spine bone mineral density (BMD) and serum calcium levels compared to those receiving oral glucose-lowering medication only." (PMID 37569816, 2023). "One participant in the placebo group did not fast at any visit due to insulin-treated diabetes mellitus, and one participant in the NR group did not fast at baseline due to omission." (PMID 38016950, 2023). "We did not detect baseline differences in insulin sensitivity between progressors and non-progressors, a finding that differs from results of an analysis of the Melbourne Pre-Diabetes Family Study and the ENDIT study cohort." (PMID 36459177, 2023). "Type I diabetes, an autoimmi = une disease, results from damage to insulin-secreting beta-cells in the Langerhans islets, while Type II diabetes, also known as non-insulin-dependent diabetic mellitus (NIDDM), is characterized by decreased insulin sensitivity in target tissues." (PMID 38020229, 2023). "For example, glucagon-like peptide 1 (GLP1), a target therapeutic peptide in the treatment of diabetes, binds to the GLP1 receptor on the surface of islet cells and then transmits signals to the nucleus via the insulin signaling pathway to activate insulin secretion and inhibit glucagon release." (PMID 37298379, 2023). "One recent study in the US Virgin Islands, found that the high rates of diabetes related morbidities after Hurricanes Irma and Maria were perceived to be due to the lack of availability of insulin." (PMID 37254127, 2023).
diabetes (continued). "In healthy people without diabetes, endogenous insulin secretion is closed off, and counterregulatory hormones (glucagon, epinephrine, and norepinephrine) are released in response to hypoglycemia." (PMID 36769430, 2023). "The DKQ assessed general diabetes knowledge, while the PCQ assessed carbohydrate food recognition, carbohydrate food counting, and the incorporation of carbohydrate counting in calculating insulin dose." (PMID 37858279, 2023). "Diabetes is a metabolic disease that results from a lack of (type 1 diabetes) or insufficient insulin production and insulin signaling (type 2 diabetes), resulting in increased blood glucose." (PMID 37378396, 2023). "T2DM is a progressive disease as the production of insulin is reduced day by day irrespective of the treatment of diabetes." (PMID 38004353, 2023). "The rates of MI during follow-up were comparable in patients with diabetes not on insulin and without diabetes (0.43%/year vs 0.40%/year; HR 1.09, 95% CI 0.64–1.85, p = 0.75)." (PMID 35976428, 2023). "High, compared to low, TMexD adherence was associated with lower concentrations of insulin and some blood lipids (LDL-cholesterol, non-HDL-cholesterol and total cholesterol), but not obesity, diabetes, hypertension or other CVD-related outcomes." (PMID 35876036, 2023). "However, upon further discussion of overall knowledge and competence in diabetes management, all clinicians reported HCL insulin systems added to their confidence." (PMID 36989019, 2023). "*P-value less than 0.01 is considered statistically significant, #DM - Diabetes mellitus, ^GDM - Gestational diabetes mellitus, √BMI - Body mass index, ⁓FPG - Fasting plasma glucose, ®HOMA IR - Homeostatic model of assessment of insulin resistance, AGEs - Advanced glycated end products." (PMID 38161906, 2023). "Furthermore, propionate has been shown to impact the development of diabetes by increasing the expression of gluconeogenic genes and AKT phosphorylation in response to insulin stimulation in HepG2 hepatocytes through the GPCR43-mediated AMPK signaling pathway." (PMID 37834439, 2023). "Our findings revealed a crucial role for BACH1 in regulating insulin signaling, suggesting that BACH1 may become a promising target for the treatment of metabolic disorders such as obesity and type 2 diabetes mellitus." (PMID 38129407, 2023). "Reduced numbers of β-cells have been identified as one of the determinants leading to the development of diabetes mellitus because there are not enough β-cells to synthesize and secrete sufficient insulin." (PMID 36614256, 2023). "Ketoacidosis and hyperglycemia quickly improved following the introduction of insulin therapy, but not the β cell function." (PMID 37082120, 2023). "Further, results from the OmniHeart trial demonstrated that replacing carbohydrate with unsaturated but not saturated fat improves insulin sensitivity in individuals with pre-hypertension or hypertension stage I without diabetes." (PMID 36495341, 2023). "Type 3c is often called brittle diabetes because glucose control is especially challenging absent an appropriate beta cell (insulin) or alpha cell (glucagon) response." (PMID 36979645, 2023). "Of note, 2 of the 15 obese subjects had type 2 diabetes mellitus, both of which were treated with metformin only (not insulin dependent)." (PMID 37857661, 2023). "Diabetes mellitus is a serious metabolic disorder characterized by high blood glucose levels and occurred when the body is not able to produce enough insulin or cannot use insulin effectively." (PMID 36770850, 2023). "Nevertheless, vanadium does not fully substitute insulin in any in vivo model of diabetes, and it is better described as having an insulin-enhancing effect." (PMID 37958659, 2023). "According to the World Health Organization, “diabetes is a chronic disease that occurs either when the pancreas does not produce enough insulin or when the body cannot effectively use the insulin it produces”." (PMID 37168309, 2023).